STAT3 (signal transducer and activator of transcription 3)
Diseases named in the same sentence as STAT3 in open-access papers (continued):
Sharing a sentence is not in itself a finding about the gene and the disease.
myocardial infarction (continued). "Conclusively, EMPA reduces myocardial infarct size in animals fed with WD through STAT3 activation and regulation of inflammatory responses in the myocardium." (PMID 29311992, 2017). "Downregulation of STAT3 is sufficient to induce dilated and adverse remodeling after myocardial infarction." (PMID 27519769, 2016). "Similar to its known beneficial functions during myocardial infarction, physiological activity of STAT3 in the heart plays a protective role in a model of myocarditis mediated by CVB3 infection." (PMID 23460527, 2013). "In this regard, it has been shown that treatment with IL-10 in a murine model of myocardial infarction inhibits inflammatory parameters and participates in the cardiac remodeling process via activation of STAT3." (PMID 24260222, 2013). "In the heart, STAT3 was shown to be protective in myocardial infarction as well as in viral-induced myocarditis." (PMID 23460527, 2013). "There and in other cardiac damages such as myocardial infarction or doxorubicin-induced cardiomyopathy, STAT3 in cardiomyocytes prevents uncontrolled fibrosis and clinical progression to DCM." (PMID 22675647, 2012). "Furthermore, in myocardial infarction models, STAT3 can co-localize with MnSOD to increase its activity." (PMID 40860187, 2025). "Notably, knock-out of endothelial STAT3 in mice resulted in reduced recovery of left ventricular function during reperfusion after myocardial infarction." (PMID 37620559, 2023). "However, subacute cardioprotection by late IPC and late RIC (ischemic conditioning is induced 24 h before myocardial infarction) involves the canonical function of STAT3 and STAT5." (PMID 37620559, 2023). "EMPA reduced myocardial infarction and lipid peroxidation in a STAT3-dependent manner." (PMID 37587757, 2023). "Besides, in other cardiac damages such as myocardial infarction or doxorubicin-induced cardiomyopathy, STAT3 in cardiomyocytes prevents uncontrolled fibrosis and clinical progression to DCM." (PMID 35676606, 2022). "However, our results point to STAT3 activation as a mechanism induced by NIL10 in cardiac protection against myocardial infarction." (PMID 36297479, 2022). "Previous studies have demonstrated that in the early stage of AMI, SGLT2 inhibitor use reduces the myocardial infarct size through activation of signal transducer and activator of transcription 3 and downregulation of inflammatory responses in the infarcted myocardium." (PMID 35571176, 2022). "Relevant studies have shown the JAK2/STAT3 pathway is involved in the signal transduction process of cardiac hyperplasia and hypertrophy induced by various factors, and its activation is observed in myocardial infarction and dilated cardiomyopathy." (PMID 35609321, 2022). "It is reported that NR4A3 overexpression could increase the activity of JAK2/STAT3 signaling in the heart of mice after myocardial infarction and alleviate the inflammatory response after myocardial infarction." (PMID 35747513, 2022). "Long non-coding RNA myocardial infarction-associated transcript (LncRNA MIAT) sponged miR-181a-5p to enhance the expression of JAK2 and thus increased the JAK2/STAT3 signaling pathway to induce inflammation and apoptosis in oxygen-glucose deprivation-induced cardiomyocyte." (PMID 36148063, 2022). "G-CSF can prevent ventricular remodeling after acute myocardial infarction and improve myocardial ischemia, which may be ascribed to direct activation of the Jak2/STAT3 pathway and promotion of local revascularization." (PMID 33817262, 2020). "In addition, the cardiac-specific knockout of STAT3 exacerbated ventricular remodeling during the subacute phase of myocardial infarction in mice." (PMID 32178385, 2020). "G-CSF administration, which could trigger STAT3-mediated myocardial regeneration as mentioned, has been performed to improve cardiac function in patients with angina and/or acute myocardial infarction." (PMID 32178385, 2020).
myocardial infarction (continued). "It is worth to note that downregulated pulmonary CAV-1 expression subjected to myocardial infarction may lead to STAT3/Cyclin pathway activation, pulmonary hypertension, and lung structural remodeling development." (PMID 32565767, 2020). "In this context, the IL-10-galectin-3 axis was recently shown to be essential for the M2 macrophage polarization after myocardial infarction in a STAT3-dependent manner, and these macrophages contributed to tissue repair by promoting fibrosis and clearance of apoptotic cells." (PMID 31709266, 2019). "Leptin signalling has been shown to ameliorate cardiac dysfunction and remodelling four weeks after myocardial infarction by increasing STAT3 phosphorylation in calorie-restricted lean and obese ob/ob mice as well as in tamoxifen-inducible leptin receptor knockout mice." (PMID 30424579, 2018). "The mechanism may be related to an increased the expression of p-JAK2 and p-STAT3 after S-post, which lead to reduced mitochondrial ROS generation and increased mitochondrial ATP content, thereby reducing apoptosis and myocardial infarct size." (PMID 28392989, 2017). "The mechanism may be related to an increased expression of p-JAK2 and p-STAT3 after S-post, which reduced mitochondrial ROS generation and increased mitochondrial ATP content, thereby reducing apoptosis and myocardial infarct size." (PMID 28392989, 2017). "The mechanism may be related to the increase in the expression of p-JAK2 and p-STAT3 after S-post, which led to reduced mitochondrial ROS generation and increased mitochondrial ATP content, thereby reducing apoptosis and myocardial infarct size." (PMID 28392989, 2017). "STAT3 KO mice also exhibited a marked increase in mortality with myocardial infarction (MI)." (PMID 26664907, 2015). "Acute STAT3 activation is known to be beneficial in myocardial infarction, but its improper activation may be detrimental to heart function." (PMID 23460527, 2013). "Thus, STAT3 deletion leads to impaired cardiac function after myocardial infarction and doxorubicin-induced cardiomyopathy." (PMID 22675647, 2012). "Moreover, O3 also activated the JAK2/STAT3 signaling, upregulated the expression of HSP70 both in vitro and vivo, and decreased the index of apoptosis of cardiomyocytes caused by I/R as well as myocardial infarct area in vivo." (PMID 34516361, 2021). "Further experimental studies showed that an inhibition of IL-10/Stat3 in myocardial tissues recruits inflammation cells, damages the function of the heart, and enhances mortality after myocardial infarction (MI) in mice." (PMID 33456490, 2020). "Previous studies have demonstrated that CCL2 expression is elevated in infarcted myocardial tissue, promoting cardiac regeneration through the activation of STAT3 signaling, thereby highlighting its potential therapeutic role in myocardial infarction (MI) and related heart failure." (PMID 40342964, 2025). "Thirdly, inflammatory signaling: In myocardial infarction models, TMAO activates JAK2-STAT3 in cardiac fibroblasts, increasing JAK2/STAT3 phosphorylation and fibronectin/collagen I/III synthesis." (PMID 41277967, 2025). "In the context of myocardial infarction, molecular factors like miR-124, IL-10, and growth arrest and DNA damage-inducible α (GADD45A) exert beneficial effects through the STAT3 pathway." (PMID 38495094, 2024). "SOCS3 expression can occur in response to cytokine-triggered STAT3 signaling or H2O2 and likely contributes to proteasomal degradation and cardiac remodeling, e.g., after myocardial infarction." (PMID 39335522, 2024). "It was shown that post-ischemic treatment could further increase STAT3 phosphorylation at tyrosine 705 and reduce the area of myocardial infarction in MI/RI pigs." (PMID 37680709, 2023). "In the LAD ligation of a rat model, as early as 5 minutes after myocardial infarction, we observed JAK2, STAT1, STAT3, STAT5a, and STAT6 phosphorylation." (PMID 34516361, 2021).
myocardial infarction (continued). "Other findings showed that miR-21 promoted cardiac fibrosis via the TGF-β/Smad7 signaling pathway after myocardial infarction and via the CADM1/STAT3 pathway in patients with atrial fibrillation." (PMID 35118144, 2021). "Evidence has demonstrated that the activation of STAT3 limits apoptosis in rat models of myocardial infarction, while others have highlighted the importance of JAK2-STAT3 activation in apoptosis of post-ischemic damage." (PMID 30384838, 2018). "A more acute administration of empaliflozin (4 or 24 h before myocardial infarction in mice), however, failed to reduce myocardial infarct size, and STAT3 was not activated." (PMID 37620559, 2023). "In contrast to the acute non-canonical and the subacute canonical STAT3 activation which serve a protective function, chronic STAT3 activation after myocardial infarction contributes to inflammatory processes and cardiac remodeling." (PMID 37620559, 2023). "The expression of STAT3 and ZFP36 was different only within 24 h after myocardial infarction." (PMID 36407421, 2022). "Myocardial infarction reduced mRNA and protein expressions of Annexin A1, signal transducer and activator of transcription 3 (STAT3) and vascular endothelial growth factor (VEGF) as well as phospho-STAT3 level." (PMID 34943928, 2021). "The present study analyzes pathomechanisms of age-related idiopathic or DCM for which pathomechanisms are different from myocardial infarction or I/R injury as, for example, canonical STAT3 signaling is not or only moderately activated." (PMID 33370269, 2020). "Oncostatin M (OSM) and IL-13 stimulate ACM cell cycle re-entry and improve cardiac function after myocardial infarction (MI) through Raf/MEK/Erk and STAT3/6 signaling pathway." (PMID 36780463, 2023). "In addition, JAK/STAT3 activation can lead to diaphragm weakness without evidence of oxidative stress, as reported in mice with cancer cachexia or myocardial infarction." (PMID 30992039, 2019). "The cardiac function indicators, myocardial infarct size, lactic dehydrogenase (LDH) release, mitochondrial ultrastructure, mitochondrial reactive oxygen species (ROS) generation rates, ATP content, protein expression of p-JAK, p-STAT3, Bcl-2 and Bax were measured." (PMID 28392989, 2017). "While, STAT3 phosphorylation is known to bestow infarct sparing properties through interaction with mitochondria, we observed that EMPA did not directly alter the mitochondrial calcium retention capacity (CRC); therefore, its effect in reducing myocardial infarction is STAT3 dependent." (PMID 29311992, 2017).
renal cell carcinoma (94 papers, 2010 to 2026). "In renal cell carcinoma, earlier studies have shown that increased STAT3 activation has been associated with progression of pathological stages and worse prognosis 33-35." (PMID 35637970, 2022). "G3BP1 also causes tumor progression and metastasis in renal cell carcinoma cells by over-expression along the IL6 / G3BP1 / STAT3 pathway." (PMID 34604242, 2021). "LINC00160 mediates sunitinib resistance in renal cell carcinoma via SAA1 that is implicated in STAT3 activation and compound transportation, which offers an opportunity for targeted intervention and molecular therapies in the future." (PMID 32921632, 2020). "In renal cell carcinoma, increased STAT3 activation is associated with increased metastasis and worse survival outcomes, but clinical trials targeting the STAT3 signaling pathway have shown varying levels of success in different RCC subtypes." (PMID 30863721, 2019). "For example, STAT3 polymorphism predicts IFNα response in patients with other tumor entities like renal cell carcinoma or chronic myeloid leukemia." (PMID 26735690, 2016). "Previously STAT3 polymorphisms had been shown to be suitable as predictive makers to analyze the response to IFN-α in renal cell carcinoma." (PMID 24624997, 2014). "The decreased risk associated with the SNPs in the STAT3 gene in our study correlates with the results of other studies, e.g. the rs12949918 SNP was found to be associated with decreased susceptibility to different malignancies, like risk to B-cell non-Hodgkin lymphoma or renal cell carcinoma." (PMID 23021489, 2012). "A recent study showed that ISG15 can promote proliferation and metastasis through IL6/JAK2/STAT3 signaling in renal cell carcinoma." (PMID 40874680, 2025). "For instance, Exosomal lncARSR promotes M2 macrophage polarization via STAT3 activation, advancing renal cell carcinoma." (PMID 40761779, 2025). "It has been reported that ILF3 /ERp57 forms a positive feedback loop mediating STAT3; therefore, ILF3/STAT3/ERp57 together promote evident renal cell carcinoma proliferation." (PMID 38136312, 2023). "Exosomes containing lncARSR secreted from renal cell carcinoma (RCC) were found to promote M2 polarization by activating the STAT3 pathway, thus favoring RCC progression." (PMID 36612282, 2022). "lncARSR-containing EVs derived from renal cell carcinoma achieve a similar effect via the STAT3 pathway." (PMID 36405712, 2022). "For example, in renal cell carcinoma, sunitinib has been shown to suppress the activation of STAT3, a nuclear transcription factor considered critical for promoting proliferation, resistance to apoptosis, and tumorigenesis." (PMID 33936816, 2021). "SIRT1 deacetylates STAT3, which promotes the degradation of STAT3 and leads to the suppression of tumorigenesis in renal cell carcinoma (RCC)." (PMID 34769241, 2021). "Evidence shows that G3BP1 promotes tumour progression and metastasis through the IL-6/G3BP1/STAT3 signalling axis in renal cell carcinoma." (PMID 33579337, 2021). "There is already a STAT3-related agent that has been approved by the FDA since 2006 for the treatment of renal cell carcinoma and imatinib-resistant gastrointestinal stromal tumor." (PMID 32257917, 2019). "We identified Stat3 signaling as a potential bypass mechanism that enables renal cell carcinoma (RCC) cells to escape dasatinib treatment." (PMID 26625308, 2015). "It has been reported that inhibition of STAT3 by sunitinib contributes to the induction of apoptosis in renal cell carcinoma." (PMID 24423131, 2013). "STAT3, a new oncogenic target in the setting of renal cell carcinoma, plays a critical role in promoting cell proliferation, metastasis and angiogenesis." (PMID 23690956, 2013).
renal cell carcinoma (continued). "Overall, these results suggest that Icaritin strongly inhibits STAT3 activation and is a potentially effective therapeutic option for the treatment of renal cell carcinoma." (PMID 24324713, 2013). "Herein, we investigated the regulation of STAT3 activation and the therapeutic effects of Icaritin, a prenyl flavonoid derivative from Epimedium Genus, in renal cell carcinoma (RCC)." (PMID 24324713, 2013). "STAT3 plays a key role in progression of renal cell carcinoma via inducing pro-angiogenic factors including VEGF." (PMID 22899991, 2012). "Concurrent inhibition of bromodomain-containing protein 4 (BRD4) and signal transductor and activator of transcription 3 (STAT3) could potentially be an effective strategy against renal cell carcinoma (RCC)." (PMID 40078291, 2025). "Subsequent investigations have shown that reducing the expression of ETK in renal cell carcinoma hinders the development and spread of cancer cells, and triggers programmed cell death, by reducing the levels of phosphorylated STAT3 (p-STAT3) and vascular endothelial growth factor (VEGF)." (PMID 38773612, 2024). "Sunitinib suppressed Stat3 expression in renal cell carcinoma‐related MDSCs." (PMID 37547175, 2023). "Sunitinib was reported to induce cell apoptosis in renal cell carcinoma via STAT3 inhibition." (PMID 36720918, 2023). "While it is known that IL-10 is one of the cytokines activating STAT3—a well-known activator of transcription that plays an important role of renal cell carcinoma development—increased STAT3 activation correlates with both advanced metastatic disease and worse survival in RCC." (PMID 37108073, 2023). "For instance, the CSF-1/CSF-1R axis could induce phosphorylation and activation of STAT3, which promotes cell survival and proliferation in renal cell carcinoma." (PMID 31565097, 2019). "Sulforaphane, an active constituent present in broccoli and cauliflower, exhibits a potent effect against several cancers, including cervical, bladder, prostate, and renal cell carcinoma, by hitting various signaling networks, such as the STAT3/HIF-1α/VEGF and Nrf2 signaling pathways." (PMID 30871059, 2019). "In addition, STAT3 promotes the progression from carcinoma in situ to invasive bladder cancer and modulates renal cell carcinoma angiogenesis by increasing the expression of HIF1α and VEGF." (PMID 28031890, 2015). "Based on these reports and the present study, we hypothesized that STAT3 would be a critical factor for the treatment of renal cell carcinoma and toxicity to skin tissue, and that responsibility of STAT3 depend on functional SNPs." (PMID 24423131, 2013). "Signal transducer and activator of transcription 3 (STAT3) regulates the expression of genes that mediate cell survival, proliferation, and angiogenesis and is aberrantly activated in various types of malignancies, including renal cell carcinoma (RCC)." (PMID 20461084, 2010). "Studies have shown that IL-6 can significantly increase proliferation and metastasis in cancers, such as renal cell carcinoma (RCC) due to the activation of JAK2/STAT3, a pro-inflammatory pathway." (PMID 39478996, 2024). "The accumulation of ROS could inactivate STAT3 activity in renal cell carcinoma (RCC)." (PMID 34277607, 2021). "For example, in renal cell carcinoma, activation of the self-ligand SLAMF7 immune receptor on T cells induces STAT1 and STAT3 phosphorylation and the expression of multiple inhibitory receptors and transcription factors associated with T-cell exhaustion." (PMID 40646691, 2025). "In renal cell carcinoma, RNF7 activates the JAK/STAT3 signaling pathway by inducing SOCS1 ubiquitination, leading to reduced cellular apoptosis." (PMID 40251202, 2025). "For instance, exosomal circSAFB2 facilitates M2 macrophage polarization in renal cell carcinoma (RCC), leading to increased immune escape and metastasis through miR-620/JAK1/STAT3 axis." (PMID 37365670, 2023).